ANXA2 (annexin A2)
Diseases named in the same sentence as ANXA2 in open-access papers (continued):
Sharing a sentence is not in itself a finding about the gene and the disease.
astrocytoma (4 papers, 2013 to 2019). "(C) ANXA2 positively correlates with miR155HG in WHOII/III astrocytoma specimens of three independent public database." (PMID 30898167, 2019). "We also found a positive correlation between ANXA2 and miR155HG in WHO II and WHO III astrocytoma patients in these independent public databases." (PMID 30898167, 2019). "GBM presented a significant higher expression of ANXA2, ANXA2P1 and ANXA2P2 than astrocytoma (A, P=0.006, P=0.030 and P=0.005, respectively) and oligodendroglioma (OD, P<0.001, P=0.004 and P<0.001, respectively)." (PMID 29291003, 2017). "The expression of ANXA2 and its pseudogenes were markedly higher in GBM samples than various low-grade gliomas (LGG, all P<0.001) that refer to some diffuse gliomas (astrocytoma, oligoastrocytoma (OA) and oligodendroglioma)." (PMID 29291003, 2017).
brain cancer (4 papers, 2009 to 2019). A primary or metastatic malignant neoplasm affecting the brain. "Thus, we have identified the miR155HG/miR-185-5p/ANXA2 loop and its mechanisms and biological effects in malignant brain tumors." (PMID 30898167, 2019). "Upregulation of annexin A2 has been reported in many malignancies, such as buccal SCC, pancreatic, gastric, breast and brain cancer." (PMID 19367286, 2009).
Breast Invasive Carcinoma (4 papers, 2020 to 2024). "Two of the top interactors identified in all three pulldowns, ANXA2 and IPO7 are also implicated in invasive breast cancers." (PMID 39353922, 2024). "Over-expression of Anxa2 in invasive breast cancer MDA-MB-231 cells accelerated NF-κB activation and the expression EMT-TFs including SLUG, SIP1 and TWIST1, followed by the down-regulation of E-cadherin and up-regulation of N-cadherin." (PMID 32244350, 2020). "The over-expression of full-length Anxa2 increased the expression of three EMT-TFs such as SLUG, SIP1 and TWIST1 and two MMPs (MMP2, MMP9) in invasive breast cancer MDA-MB-231 cells." (PMID 32244350, 2020).
cholangiocarcinoma (4 papers, 2024 to 2025). A carcinoma that arises from the intrahepatic biliary tree (intrahepatic cholangiocarcinoma) or from the junction, or adjacent to the junction, of the right and left hepatic ducts (hilar cholangiocarcinoma). "Next, failed axon connection homolog (FAXC), a homolog of Fax in Drosophila, enhanced Anxa2 phosphorylation at mitochondria, which was essential for cholangiocarcinoma (CCA) development." (PMID 39912333, 2025).
coronary artery disease (4 papers, 2013 to 2023). "Epicardial adipose tissue demonstrated a procalcifying proteomic profile in patients with coronary heart disease, with increased regulation of annexin A2 and decreased regulation of fetuin-A protein." (PMID 34948066, 2021).
cytomegalovirus infection (4 papers, 2004 to 2024). A herpesvirus infection caused by Cytomegalovirus. "An additional reovirus resistant-clone with an insert in the Anxa2 (annexin 2) gene, associated with cytomegalovirus infection and recognized to bind to the insulin and insulin growth factor receptor-1, also failed to grow in soft agar." (PMID 15333144, 2004). "In addition, endogenous ANXA2 promotes CMV infection, and in turn, CMV infection promotes the expression of ANXA2, which can activate human γδ T cells by recognizing cellular receptors, thereby inducing an inflammatory response." (PMID 39057791, 2024). "Some studies showed that virion incorporated Annexin A2 could accelerate fusion of membranes during entry in accordance with the observation that some Annexin A2 specific antibodies could inhibit HCMV infection." (PMID 24386290, 2013).
depression (4 papers, 2020 to 2025). "This contradicts our research findings that elevated ANXA2 expression is associated with depression." (PMID 37690046, 2023). "Given the critical roles for Ahnak in scaffolding and stabilizing p11 and Anxa2 proteins and in regulating L-type VGCCs, we examined whether the loss of Ahnak results in depression-like or antidepressant-like behaviors by measuring depression-related behaviors." (PMID 30760886, 2020). "To clarify how ANXA2 alleviates depression-like behaviours caused by CRS or HDAC9 overexpression, we examined whether ANXA2 plays a role in dendritic spine development in the hippocampus." (PMID 37690046, 2023). "However, some studies from the Yong Kim’s group found that reduced levels of ANXA2 increase depression." (PMID 37690046, 2023). "HDAC9 upregulation may protect ANXA2 from ubiquitin-dependent degradation, thereby contributing to depression-like symptoms." (PMID 37690046, 2023). "Meanwhile, the components of the p11/ANXA2 protein complex stabilize each other in cells, and the protein levels of p11 decreased in various tissues from ANXA2 KO mice, suggest that ANXA2 may play a role in depression through p11." (PMID 37690046, 2023). "Of note, the GABAergic interneurons involved in depression express SMARCA3 and mediate the response to antidepressants through the p11/annexin A2/SMARCA3 complex." (PMID 38092990, 2025). "In summary, our findings suggest that HDAC9 in hippocampal neurons may play a role in the pathophysiology of depression and that HDAC9 regulates the acetylation and ubiquitination of ANXA2." (PMID 37690046, 2023). "Although there is currently a lack of clear research on ANXA2 in depression, p11 is considered a key targets in depression research." (PMID 37690046, 2023).
epilepsy (4 papers, 2020 to 2024). A brain disorder characterized by episodes of abnormally increased neuronal discharge resulting in transient episodes of sensory or motor neurological dysfunction, or psychic dysfunction. "Hence, the study aimed at investigating the underlying role of ANXA2 in epilepsy through behavioral, electrophysiological, and pathological analyses." (PMID 37302990, 2023). "Given that synaptic dysfunction is closely associated with epilepsy and that previous reports indicate that ANXA2 plays a major role in the development of excitatory synaptic activity, we speculate that ANXA2 can participate in epileptogenesis by regulating synaptic transmission." (PMID 37302990, 2023). "This interaction was confirmed by COIP, indicating that GluA1 is a downstream target of ANXA2 in our epilepsy model." (PMID 37302990, 2023). "By reporting a previously unrecognized and important role of ANXA2 in epilepsy, we first found that ANXA2 was highly expressed in the brain tissues of TLE patients and KA‐induced epileptic mice." (PMID 37302990, 2023). "In conclusion, this research focuses on how ANXA2 mediates excitatory synaptic activity in epilepsy and also provides novel clues for alternative epilepsy therapies." (PMID 37302990, 2023). "In summary, we can conclude that ANXA2 mainly mediates excitatory synaptic transmission activity in epilepsy and inhibiting ANXA2 activity has an antiepileptic effect." (PMID 37302990, 2023). "The findings establish ANXA2 as a novel target for potential epilepsy therapies." (PMID 38639785, 2024). "Elevated ANXA2 expression was detected in epilepsy patients and models, both in vivo and in vitro." (PMID 38639785, 2024). "Nevertheless, the impact of ANXA2 on epilepsy remains to be clarified." (PMID 37302990, 2023). "Moreover, the effects of ANXA2 on epilepsy were examined through behavioral and electrophysiological analyses of KA‐induced mouse." (PMID 37302990, 2023). "This study covers a previously unknown and key function of ANXA2 in epilepsy." (PMID 37302990, 2023). "In this study, the protein expression of ANXA2 was detected in intractable TLE patients, in epilepsy mouse models, and in vivo hippocampal neurons' model." (PMID 37302990, 2023). "First, elevated ANXA2 protein expression was detected in TLE patients and epilepsy models in vivo and in vitro." (PMID 37302990, 2023). "It was found that ANXA2 was markedly upregulated in the cortical tissues of temporal lobe epilepsy patients (TLE), kainic acid (KA)‐induced epilepsy mice, and in a seizure‐like model in vitro." (PMID 37302990, 2023). "ANXA2 promotes phosphorylation of the AMPAR subunits GluR1‐S845 and GluR1‐S831, resulting in increased AMPAR membrane protein expression and enhanced excitatory synaptic transmission in neurons, which is involved in epilepsy formation." (PMID 37302990, 2023). "The 5 Hub genes, including C3, CD44, ANXA2, HTR1E, and APP, were also identified as the BottleNeck genes, that is, they are Hub-BottleNeck genes, indicating that they are much more important than the remaining Hub genes in the pathogenesis of epilepsy in PT." (PMID 33123575, 2020). "Based on the data that the expression levels of S845 and S831 were reduced after ANXA2 knockdown, it was found that PKA‐targeted phosphorylation of GluA1 S845 and PKC‐targeted phosphorylation of GluA1 S831 were more effective than PP1 dephosphorylation in epilepsy." (PMID 37302990, 2023).
gallbladder cancer (4 papers, 2014 to 2024). "By sponging miR-206, MALAT1 up-regulates ANXA2 and KRAS expression in gallbladder cancer cells, and reduces CDC42 and up-regulates CDK4 expression in breast cancer cells." (PMID 32174966, 2020). "By functioning as a ceRNA for miR-206, MALAT1 up-regulates the expression of the oncogenic ANXA2 and KRAS, and promotes gallbladder cancer cell proliferation and invasion in vitro and tumor progression in mice." (PMID 32174966, 2020). "Serial analysis of gene expression showed that upregulation of ANXA2 activates RPS6KA1, a downstream component of the MAPK signaling pathway, thereby affecting the development and progression of gallbladder cancer." (PMID 25362534, 2014). "Moreover, TAM-derived CCL18 can stimulate Annexin A2 (AnxA2), which then activates the EMT through the PI3K/Akt/GSK3β/Snail pathway in BC, and similar activation of PI3K/Akt in gallbladder cancer (GBC) promotes cell migration." (PMID 39286635, 2024).
gastric tumors (4 papers, 2011 to 2024). "The research of the role of ANXA2 in gastric tumors has been more extensive, with several studies reporting its up-regulation in GC tissues compared to normal tissues, which they associated with various clinicopathological features of GC and a poor prognosis." (PMID 39594718, 2024). "We observed that the total levels of ANXA2 were unchanged in all colon samples and moderately elevated in the gastric tumor." (PMID 22185818, 2011). "We also investigated the redox status of ANXA2 in colon and gastric tumors compared to adjacent normal tissue." (PMID 22185818, 2011).
head and neck squamous cell carcinoma (4 papers, 2013 to 2023). A squamous cell carcinoma that arises from any of the following anatomic sites: lip and oral cavity, nasal cavity, paranasal sinuses, pharynx, larynx, and salivary glands. "As both ANXA1 and ANXA2 have been found down-regulated in head and neck squamous cell carcinoma, it was of special interest to determine whether ANXA9 showed a similar pattern of expression as this might relate to common features in the evolution, structure and function of these clade members." (PMID 30744186, 2019).
Insulin resistance (4 papers, 2012 to 2024). Increased resistance towards insulin, that is, diminished effectiveness of insulin in reducing blood glucose levels. "Furthermore, AnxA2 interacts with galectin-3 at the cell surface, which directly induces cellular insulin resistance and associated inflammation under obese conditions by impairing insulin signaling." (PMID 34681689, 2021). "Two proteins involved in the insulin pathway (Annexin A2 and 14-3-3 ζ/δ) were found to be differentially expressed in the present study, and therefore may be directly associated with insulin resistance in GDM." (PMID 22970290, 2012). "In a high-fat diet induced IR mouse model study, silencing AnxA2 attenuated the obesity-induced insulin resistance and inflammation through the process of p50 nuclear translocation of the NF-κB signaling pathway." (PMID 34681689, 2021). "Additionally, further studies are warranted to explain the mechanism of resistance exercise training in decreasing the PCSK9 level, especially via the proposed mechanism such as Annexin A2, adiponectin, and insulin resistance measured with HOMA-IR." (PMID 37946122, 2023).
malaria (4 papers, 2014 to 2024). Malaria is a serious and sometimes fatal disease caused by a parasite that commonly infects a certain type of mosquito which feeds on humans. "In addition, this study indicated that the lower expression of ANXA2 protein might also activate asthma, ECM-receptor interaction, leishmaniasis, malaria, and renin-angiotensin system (RAS) pathways, all of which might potentially regulate HCM treatment." (PMID 38277535, 2024).
preeclampsia (4 papers, 2021 to 2024). Preeclampsia is a hypertensive disorder of pregnancy that is characterized by new-onset hypertension with proteinuria presenting after 20 weeks of gestation, and depending on mild or severe forms may initially present with severe headache, visual disturbances, and hyperreflexia. "ANXA2 inhibition in endometrial stromal cells decreases embryo invasion in vitro, impairs decidualization, and contributes to the pathogenesis of severe preeclampsia." (PMID 34980157, 2022). "In concert with our finding, ANXA2 levels were suppressed during in vitro decidualization of human endometrial stromal cells in the context of severe preeclampsia." (PMID 34055578, 2021). "Defective expression of endometrial ANXA2 may impair decidualization of endometrial stromal cells in vitro and in vivo, leading to the development of preeclampsia." (PMID 39399103, 2024).
renal carcinoma (4 papers, 2009 to 2023). A carcinoma arising from the epithelium of the renal parenchyma or the renal pelvis. "Of note, Anxa2 can be an injury index to predict the prognosis of chronic glomerular diseases or renal cancer." (PMID 37955107, 2023). "Aberrant expression of ANXA2 has been detected in numerous kidney diseases, including primary and secondary nephropathy, acute kidney injury, chronic kidney disease, as well as kidney carcinoma." (PMID 36120574, 2022).
varicocele (4 papers, 2020 to 2025). A condition characterized by the dilated tortuous veins of the spermatic cord with a marked left-sided predominance. "WB analysis of acetylated ANXA2 further endorsed the role of acetylation by inducing more apoptotic sperm death in bilateral varicocele." (PMID 32365753, 2020). "Further, WB analysis of the immunoprecipitated proteins ANXA2 and SERPINB6 involved in the same network confirmed the proteins associated with the oxidative stress response are acetylated in the spermatozoa of varicocele patients." (PMID 32365753, 2020). "Based on these findings, it has been proposed that KIF5B and ANXA2 could be considered potential biomarkers for exosomal dysfunction in patients with varicocele." (PMID 41222141, 2025). "Among the altered proteins, several exosomal proteins including Annexin A2 (ANXA2), Transferrin (TF), Kinesin‐1 heavy chain (KIF5B), and semenogelin 1 (SEMG1) were found to be consistently expressed differently in the seminal plasma of patients with unilateral varicocele." (PMID 41222141, 2025).
acute lymphoblastic leukemia (3 papers, 2014 to 2024). Leukemia with an acute onset, characterized by the presence of lymphoblasts in the bone marrow and the peripheral blood. "Vice versa, disruption of AnxA2/p11 interaction with small molecule inhibitors or AnxA2 antibodies reduced acute lymphoblastic leukemia proliferation and sensitized tumour cells to chemotherapy." (PMID 33810523, 2021). "Here we show that activation of plasmin, a key fibrinolytic agent, by annexin A2 (ANXA2) distinctly impacts progression of BCR-ABL1+ B-cell acute lymphoblastic leukemia (B-ALL) via modulation of the extracellular matrix (ECM) in the BMM." (PMID 39567540, 2024).
acute myeloid leukemia (3 papers, 2021 to 2023). Acute myeloid leukemia (AML) is a group of neoplasms arising from precursor cells committed to the myeloid cell-line differentiation. "The implication of pseudogene-derived altProts is emphasized by the association of three of them with acute myelocytic leukemia through their interaction with ANXA2 (cluster #508)." (PMID 36183975, 2023). "ANXA2 was downregulated in adrenocortical carcinoma (ACC), KICH, acute myeloid leukemia (LAML), PRAD and skin cutaneous melanoma (SKCM)." (PMID 36713082, 2023).
acute renal failure (3 papers, 2014 to 2024). "ANXA2 may contribute to several other kidney diseases, such as diabetic nephropathy or acute kidney injury." (PMID 38891801, 2024). "It appeared that ANXA2 is the sensor of tubular injury and recovery in the acute renal failure." (PMID 36120574, 2022). "We also identified another member of the annexin family, annexin A2 (ANXA2), as an early sensor of tubular injury that persists throughout the recovery process of tubular cells in acute renal failure and is upregulated in both the glomerulus and renal tubules in crescentic glomerulonephritis." (PMID 24591769, 2014).
aortic aneurysm (3 papers, 2022 to 2025). A ruptured aneurysm located in the wall of the proximal portion of the descending aorta proceeding from the arch of the aorta. "We identified a subpopulation of the Trem2 macrophage featured biological function on macrophage migration and expression of SPP1, TREM2, FABP5, and ANXA2 in both organisms during the pathology of aortic aneurysm." (PMID 36703732, 2022). "Annexin II (annexin A2) is reportedly highly expressed in the aortic wall of a rat model of aortic aneurysm, while immunohistological studies showed heavy staining for annexin II in the shoulder region of atheromatous plaque from human aortic aneurysm wall tissue." (PMID 35163216, 2022).
Cerebral ischemia (3 papers, 2023 to 2025). Restriction of arterial blood supply to the brain associated with insufficient oxygenation to support the metabolic requirements of the tissue. "Compared to WT mice, Lrg1−/− mice exhibited increased protein levels of cell adhesion-related molecules, including Cldn11, Anxa2, Pcdh9, and Itgb5, in endothelial cells after cerebral ischemia‒reperfusion injury." (PMID 38037097, 2023). "Notably, the role of Anxa2 in cerebral ischemia/hypoxia is controversial." (PMID 39912333, 2025). "Thus, our findings reveal a critical role of microglial Anxa2 in regulating the inflammatory response, suggesting that Anxa2 may be a potential therapeutic target for cerebral ischemia." (PMID 38253182, 2024). "Single-cell RNA sequencing analysis of WT and Lrg1−/− mouse brain tissues after cerebral ischemia‒reperfusion injury revealed that Lrg1 knockout enhances blood‒brain barrier (BBB) by upregulating claudin 11, integrin β5, protocadherin 9, and annexin A2." (PMID 38037097, 2023). "We believe that Lrg1 knockout may regulate the expression of critical junction molecules, such as Cldn11 and Anxa2, affecting their protein expression and ultimately preserving BBB stability after cerebral ischemia‒reperfusion injury and reducing brain edema." (PMID 38037097, 2023).
chronic pancreatitis (3 papers, 2015 to 2024). A chronic inflammatory process causing damage and fibrosis of the pancreatic parenchyma. "To explore the role of Hspb1 in SAP, we used Hspb1 knockout (KO) mice, a genetically engineered chronic pancreatitis strain (T7D23A), Anxa2 KO mice, and acinar cell-specific Prdx1 knockout mice." (PMID 38481805, 2024).
ductal carcinoma in situ (3 papers, 2015 to 2022). "We observed that Anxa2 expression was negative in normal breast ducts, moderately positive in ductal carcinoma in situ, and strongly positive in most of the invasive cancer (76/85)." (PMID 26307676, 2015).